HMGB1 (high mobility group box 1)
Diseases named in the same sentence as HMGB1 in open-access papers (continued):
Sharing a sentence is not in itself a finding about the gene and the disease.
renal disease (41 papers, 2011 to 2026). "HMGB1, a widely available protein, is a potential inflammatory cytokine associated with many kidney diseases." (PMID 40872555, 2025). "In various kidney diseases, HMGB1 and its receptors have been implicated in triggering ER stress in renal tubular cells, consequently exacerbating the progression of renal injury." (PMID 40727103, 2025). "As a potential inflammatory cytokine, HMGB1 is closely associated with many kidney diseases." (PMID 35960478, 2023). "In accordance with these studies, HMGB1 plays central role in the pathogenesis of kidney diseases, including DN." (PMID 37498374, 2024). "Several clinical studies have also shown that elevation of the HMGB1 level is significantly correlated with kidney disease progression." (PMID 38481996, 2024). "In kidney disease, serum HMGB1 levels are significantly elevated and show differences in different pathologies." (PMID 38481996, 2024). "Accumulating evidence has revealed that the expression of HMGB1 in the blood, urine, kidney tissue, cytoplasm, and extracellular matrix is increased in patients with kidney disease." (PMID 35960478, 2023). "Increased concentrations of HMGB1 have been observed in both serum and urine among individuals with renal diseases." (PMID 38201260, 2023). "HMGB1 can activate M1 macrophages in mouse models of ischemia-reperfusion and obstruction kidney disease and in vitro." (PMID 38022581, 2023). "More importantly, HMGB1 plays a distinct role in the chronic pathophysiology of kidney disease, which differs from that in acute lesions." (PMID 37781525, 2023). "HMGB1 regulates cellular proliferation, differentiation, tissue regeneration and inflammation, which contributes to kidney disease pathogenesis." (PMID 36712653, 2022). "Regarding HMGB1 functions, including inflammation, proliferation, and tissue regeneration in the pathogenesis of renal diseases, the main function of HMGB1 in cytoplasm is known to limit apoptosis." (PMID 35712799, 2022). "Multiple studies have shown that serum HMGB1 is predictive of the outcomes of end-stage liver and renal disease." (PMID 36712653, 2022). "For example, CHOP deficiency inhibited fibrosis via Hmgb1/TLR4/NFκB signalling through a CHOP-related ERS pathway; ERS caused tubular damage in kidney disease; and irreversible ERS caused kidney cell apoptosis and, consequently, fibrosis." (PMID 36142626, 2022). "In renal diseases, immune cells recruited to the nephrons release S100 proteins and HMGB1, inducing ROS and inflammation, thus generating additional AGEs that crosslink local ECM proteins and induce amyloid fibril formation." (PMID 34204735, 2021). "HMGB1 is a key inflammatory cytokine involved in kidney diseases, and Nrf2 is considered a master regulator of cellular redox signaling, inflammatory pathway." (PMID 32318235, 2020). "High mobility group box 1 (HMGB1) is a nuclear DNA-binding protein that plays an important role in the pathogenesis of kidney diseases mediated by its proinflammatory effects." (PMID 29922171, 2018). "Acetylation of high-mobility group box 1 (HMGB1) protein is a crucial process prior to its transfer from the nucleus to the cytoplasm and extracellular secretion in renal cells, which accelerates the progression of renal disease." (PMID 38347622, 2024). "So, HMGB1/TLR4/NF-κB is an important inflammatory signal pathway in renal disorders." (PMID 37498374, 2024). "HMGB1 is expressed by many renal cell types and serves as a damage-associated molecular pattern molecule (DAMP) in the extracellular environment, thereby contributing to pathogenesis in various renal diseases." (PMID 38201260, 2023). "Some studies have revealed that HMGB1 plays a role in the pathogenesis of renal disease and have suggested that inhibiting the release of HMGB1 could exert a protective effect against the development of AKI." (PMID 32957908, 2020).
renal disease (continued). "Extracellular HMGB1 plays a role as a cytokine in inflammation and cell migration, while plasma HMGB1 level is an indicator of disease severity, such as brain, cardiovascular, and renal diseases." (PMID 30944548, 2019). "Nevertheless, increased urine levels of HMGB1 might indicate that HMGB1 is an important inflammatory mediator and that urinary HMGB1 might be an additional biomarker for assessment of renal disease activity in SLE." (PMID 22892043, 2012). "However, in selected patients with active disease, both those with renal and non-renal disease activity had decreased HMGB1 levels (1.2 ng/ml (0 to 47.2)) and 2.3 ng/ml (0.95 to 12.5), respectively) compared to HC." (PMID 21548924, 2011). "In the present study, we were not able to determine whether serum levels of HMGB1 could be used for monitoring of renal disease activity per se but found persistently elevated levels of serum as well as tissue expression, suggesting that HMGB1 is an important inflammatory mediator in LN." (PMID 22348591, 2012). "The present study demonstrates an increase in HMGB1 levels in SLE patients, in particular in those with active renal disease." (PMID 21548924, 2011). "Levels of HMGB1 in the sera of SLE patients, in particular in those with active renal disease, are increased." (PMID 21548924, 2011). "The acetylation of high-mobility group box 1 (HMGB1) is a pivotal step required for its nuclear export, cytoplasmic translocation, and subsequent extracellular secretion in renal cells, a process that exacerbates the progression of renal diseases." (PMID 39911234, 2024). "In accordance with our previous study, serum levels of HMGB1 were significantly increased in active LN patients compared to patients without active renal disease and controls." (PMID 22892043, 2012). "We were not able to determine prospectively if urine levels of HMGB1 can be used for monitoring renal disease activity in patients with active LN." (PMID 22892043, 2012). "Furthermore, serum HMGB1 levels in SLE patients with active renal disease (42.5672 ± 21.0052 ng/mL) were significantly higher than those in patients without active renal disease (15.7279 ± 8.8412 ng/mL, P < 0.05)." (PMID 26078984, 2015). "Moreover, we could demonstrate that serum levels of HMGB1, in particular, were increased in SLE patients with active renal disease and correlated with proteinuria." (PMID 22892043, 2012). "To evaluate the importance of anti-HMGB1 antibodies in renal SLE, we compared anti-HMGB1 antibody levels in patients meeting the ACR-82 classification criterion for renal disorder and patients who did not fulfil this criterion." (PMID 26596890, 2015). "We observed that even though a significant correlation was found between HMGB1 and CRP levels at presentation, only AAV patients without active renal disease had significantly higher serum HMGB1 levels than HC." (PMID 24007972, 2013). "In the present study, we verified through cell experiments that miR-216a-5p, a novel miRNA never analyzed in the context renal diseases, could protect against HG-induced HMC injury by targeting the HMGB1/RAGE pathway, thus holding promise as a candidate for further investigation." (PMID 41163685, 2025).
bacterial infection (39 papers, 2010 to 2025). "Immune cells secrete HMGB1 in response to a variety of stimuli, such as pathogen associated molecular patterns (e.g. lipopolysaccharide) and bacterial infections." (PMID 36071400, 2022). "The main cause of AKI is bacterial infection, which worsens circulatory dysfunction through the release of HMGB1 and IL-6." (PMID 33061824, 2020). "Furthermore, as compared to the HMGB1-sufficient Tg+ mice, the airway epithelial cell-specific HMGB1-deficient Tg+ mice exhibited poor resolution of spontaneous bacterial infection." (PMID 36741411, 2022). "The concentration of HMGB-1 was associated with both viral and bacterial infection." (PMID 34638953, 2021). "Moreover, HMGB1 has been implicated in several bacterial diseases that are mediated by inflammatory responses." (PMID 27667993, 2016). "During the early stages of a bacterial infection, the immune system recognises the pathogens and releases high-mobility group box-1 (HMGB-1), which is crucial for immunity." (PMID 39416736, 2024). "During bacterial infection, HMGB1 enhanced the immune response of PBLs and repressed bacterial invasion." (PMID 36140677, 2022). "HMGB1 is produced by macrophages in response to bacterial infections, functioning as an endotoxin-induced cytokine mediator of inflammation, and has been proposed a potential therapeutic target for sepsis." (PMID 35173190, 2022). "HMGB1 is also actively released in low concentrations by responding innate immune cells, such as macrophages, early during bacterial infection." (PMID 34152806, 2021). "The results suggest that ODSH can significantly decrease bacterial infection-induced lung injury in CF mice by decreasing both HMGB1-mediated impairment of macrophage function and the interaction of HMGB1 with membrane receptors." (PMID 34271850, 2021). "New data suggest that the CXCR4 receptor in neutrophils is required to form NETs during bacterial infection or high-mobility group box 1 (HMGB1)-related cell death." (PMID 34948374, 2021). "Our results showed that HMGB1 production was increased by PM2.5-exposure or bacterial infection but decreased by PM2.5 + pneumococcus co-treatment." (PMID 32753046, 2020). "HMGB1 appears to significantly manipulate macrophage proinflammatory cytokine production during bacterial infection." (PMID 32753046, 2020). "The improved lung function in GTS-21 treated animals with bacterial infection is correlated with a decrease in HMGB1 accumulation in the airways." (PMID 33126860, 2020). "The abundance of HMGB1 in GCF in chronic periodontal patients suggests that human gingival epithelial cells secrete HMGB1 up on stimulation by bacterial infection." (PMID 32760399, 2020). "80% of the monocytes expressed TLR4 and thus were responsive to danger signals from bacterial infection derived LPS as well as from endogenously derived stress signals like HMGB1 and hsp." (PMID 25254631, 2014). "Increasing evidences suggest that inhibition of the alarmin HMGB1 in P. aeruginosa infection could offer a potential therapeutic strategy to reduce bacterial infection and lung inflammation." (PMID 36071400, 2022). "Since bacterial infection induced HMGB1 release, we examined whether HMGB1 could directly interact with bacteria." (PMID 36140677, 2022). "In addition, extracellular HMGB1 impairs macrophage phagocytosis and host defense against bacterial infection in mouse models of VAP and CF." (PMID 33126860, 2020). "Overall, targeting pathways to attenuate the accumulation of extracellular HMGB1 by GTS-21 may be a novel approach to develop therapies to treat bacterial infections in patients with VAP." (PMID 33126860, 2020). "HMGB-1 values from the culture supernatant were significantly increased in HUVECs stimulated with sera from KD patients before IVIG compared with those from bacterial infections (n = 16, median 5.8 ng/ml vs. n = 6, 3.3 ng/ml, P < 0.001)." (PMID 28255175, 2017).
bacterial infection (continued). "Despite HMGB1's direct link to necrosis and pro-inflammatory actions, there are, to the best of our knowledge, no clinical data to support these mechanistic actions in necrotizing bacterial infections." (PMID 24524027, 2014). "In addition, extracellular HMGB1 impairs macrophage clearance of apoptotic neutrophils, which may exacerbate bacterial infections by producing inflammatory tissue injury." (PMID 33126860, 2020). "However, little is known about HMGB1 in necrotizing bacterial infections." (PMID 24524027, 2014). "This work established the efficacy of treating inflammation in chronic respiratory diseases, including bacterial infections, by topical delivery in the lung of PAM, an inhibitor of HMGB1." (PMID 36071400, 2022). "To elucidate the direct mechanical effects of bacterial infection, we employed antibody neutralization of HMGB1 and siRNA for RAGE and demonstrated that H. pylori-induced RAGE following the elevation in HMGB1 levels." (PMID 27667993, 2016). "Compared to HMGB1, the research on fish HMG20A is limited to Nile tilapia (Oreochromis niloticus), in which it was shown that HMG20A knockdown improved fish survival after bacterial infection." (PMID 36140677, 2022). "Since HMGB1/HMG20A interacted with both PBLs and bacterial pathogens, we investigated whether these proteins could affect the bacterial infection of PBLs." (PMID 36140677, 2022). "HMGB1 also has important protective function in the colonic epithelium, because colonocyte HMGB1 was found to be directly involved in the suppression of STAT3 activation and the protection of intestine from bacterial infection and injury." (PMID 33193406, 2020). "Also similar to HMGB-1, NCAMP-1 is constitutively found in “normal” fish serum and is upregulated following bacterial infections." (PMID 25689842, 2015). "The role of HMGB1 in patients with various bacterial infections is not established." (PMID 30194360, 2018).
neurodegenerative disease (38 papers, 2013 to 2025). A disorder of the central nervous system characterized by gradual and progressive loss of neural tissue and neurologic function. "The HMGB1 pathway has been implicated in several diseases, including neurodegenerative diseases like AD." (PMID 39347125, 2024). "The high-mobility group box 1 (HMGB1) protein, a key initiator and activator of a neuroinflammatory response, has been linked to the development of neurodegenerative diseases such as AD." (PMID 38947632, 2024). "HMGB1 can act as a DAMP to promote the inflammatory response associated with many neurodegenerative diseases." (PMID 35456925, 2022). "The alarmins and signaling pathways more frequently associated with the neurodegenerative diseases comprise β-amyloid, α-synuclein, defensins, exogenous S100B, HMGB1, Hsp, and IL-33." (PMID 33114371, 2020). "HMGB1 is important in oxidative stress signaling, as well as in autophagy and apoptosis, whereas the mechanisms of autophagy and apoptosis in neurodegenerative diseases are associated with metabolic impairment." (PMID 33114371, 2020). "During the inflammatory process, HMGB1 is secreted from necrotic cells and binds to many receptors, which triggers the release of many cytokines that cause inflammation and the development of neurodegenerative diseases, including IL-6, TNFα, and IL-1β." (PMID 41351800, 2025). "The refinement of HMGB-1 expression may be a useful tool for modulating neuro-inflammatory responses, thereby attenuating a thrombin-associated central nervous system degenerative disorder cascade." (PMID 37628850, 2023). "Targeting HMGB1 for therapeutic intervention presents significant clinical potential, offering a new avenue for the treatment of neurodegenerative diseases." (PMID 39507236, 2024). "Conversely, the expression of HMGB1, a trigger of inflammation in many neurodegenerative diseases, was slightly reduced." (PMID 38469559, 2024). "Furthermore, HMGB1 acts as a potent proinflammatory mediator, activating immune cells locally in the gut and systemically, which can cause moderate gastrointestinal inflammation linked to neurological conditions like anxiety, depression, and neurodegenerative diseases." (PMID 39347125, 2024). "Some authors have evaluated, on animal models, the possible efficacy of anti-HMGB1 antibodies for treating various neurodegenerative diseases." (PMID 37508573, 2023). "The expression of HMGB1 and S100B was increased in neuron and glial cells in many neurodegenerative diseases, leading to excessive release of them and activation of RAGEs." (PMID 37433768, 2023). "DAMPs, such as HMGB1, S100, and heat shock proteins, have an important role in the inflammatory pathway of many neurodegenerative diseases and a variety of stresses." (PMID 33530496, 2021). "The elevation in HMGB1 levels was observed not only in the animal model of tau overexpression but also in other neurodegenerative diseases." (PMID 34539383, 2021). "This research paves the way for the multiple-target treatment of neurodegenerative diseases and offers insight into the complexity of p-tau-HMGB1 interactions." (PMID 34539383, 2021). "Another mediator between HMGB1 and APP was receptor for advanced glycation end products (RAGE), which has been implicated in various neurodegenerative diseases, such as AD." (PMID 33946401, 2021). "In this study, we focused on the high-mobility group box 1 (HMGB1) protein, which is important in oxidative stress signaling as well as in autophagy and apoptosis, to explore whether the mechanisms of autophagy and apoptosis in neurodegenerative diseases are associated with metabolic impairment." (PMID 26565401, 2015). "Research indicates that blocking HMGB1 release or inhibiting its signaling pathways could be a promising therapeutic strategy for these neurodegenerative diseases." (PMID 39507236, 2024).
neurodegenerative disease (continued). "Therefore, the role of HMGB1 in neurodegenerative diseases extends beyond its pro-inflammatory functions, contributing to the acceleration of neuronal degeneration and death." (PMID 39507236, 2024). "HMGB1 is pro-inflammatory in neurodegenerative diseases such as Alzheimer's disease." (PMID 37863934, 2023). "In addition, we explored the therapeutic strategy of HMGB1 inhibitors to elicit neuroprotective effects in neurodegenerative diseases with tau overexpression." (PMID 34539383, 2021). "The blockage of both apoptosis and autophagy by inhibition of HMGB1 suggests that HMGB1 might be suitable target for a neuroprotective therapy for many neurodegenerative diseases." (PMID 26565401, 2015). "Furthermore, we show that elevated levels of HMGB1 have a neuroprotective capacity that might be relevant for novel therapeutic approaches in neurodegenerative diseases." (PMID 26565401, 2015). "Overall, the roles of HMGB1, BRD4 and SOX11 as key regulators in the GRN for contrasting DEGs suggests these genes may be key drivers of associated differential alterations in neuroinflammatory, epigenetic and adult neurogenesis-related processes in neurodegenerative diseases." (PMID 41318503, 2025). "According to recent research, HMGB1 binds to receptors like TLR4 and RAGE to serve as a mediator that promotes inflammation, contributing to neurodegenerative diseases like AD." (PMID 39347125, 2024). "Studies have shown that cytokines released from neurons, including CCL2, CCL21, HMGB1, CGRP, Substance P, CX3CL1, MMP2, and MMP9, can mediate microglia activation in brain injury, neuropathic pain, or neurodegenerative diseases." (PMID 36131309, 2022). "The high mobility group box 1 (HMGB1) protein, an initiator and activator of neuroinflammatory responses, has been involved in the pathogenesis of neurodegenerative diseases, including AD." (PMID 32046119, 2020). "Given the multifaceted role of HMGB1/DSP1 in neurodegeneration, targeting of HMGB1/DSP1 may represent a novel therapeutic strategy for combating neurodegenerative diseases." (PMID 39003465, 2024). "Therefore, the results suggest that CSF HMGB1 could be a marker of progression of neurodegeneration regardless of the type of neurodegenerative disease." (PMID 27557632, 2016).